DLG3 (discs large MAGUK scaffold protein 3)
Description:
Required for learning most likely through its role in synaptic plasticity following NMDA receptor signaling.
Synonyms: SAP-102; SAP102; KIAA1232; NE-Dlg; NEDLG; MRX90; PPP1R82; MRX; XLID90; XLMR
Tractability: Small molecule: it has a binding pocket of medium quality. Antibody: its Gene Ontology location is reachable by antibodies, with high confidence. PROTAC: ubiquitination databases record sites on it; its protein half-life has been measured.
Gene: Protein-coding gene on chromosome X (70,444,835 to 70,505,490, forward strand). Ensembl gene ENSG00000082458.
Subcellular location (Human Protein Atlas): Nucleoli; Nucleoplasm
Pathways (Reactome):
Neuronal System: Activation of Ca-permeable Kainate Receptor; Assembly and cell surface presentation of NMDA receptors; Long-term potentiation; Negative regulation of NMDA receptor-mediated neuronal transmission; Neurexins and neuroligins; Ras activation upon Ca2+ influx through NMDA receptor; Synaptic adhesion-like molecules; Unblocking of NMDA receptors, glutamate binding and activation
Developmental Biology: NrCAM interactions
Signal Transduction: RAF/MAP kinase cascade
Gene Ontology:
Molecular function: kinase binding; phosphatase binding; protein binding; ionotropic glutamate receptor binding; protein kinase binding
Biological process: cell-cell adhesion; chemical synaptic transmission; establishment or maintenance of epithelial cell apical/basal polarity; negative regulation of cell population proliferation; nervous system development; protein localization to synapse; receptor clustering; receptor localization to synapse; regulation of postsynaptic membrane neurotransmitter receptor levels
Cellular component: extracellular region; adherens junction; basolateral plasma membrane; cytosol; neuromuscular junction; neuron projection; plasma membrane; postsynaptic density membrane
Gene-disease validity (ClinGen):
ClinGen rates the evidence that DLG3 causes each of these diseases.
non-syndromic X-linked intellectual disability (X-linked): Definitive.
Homologues: Orthologues: dog DLG3 (99% identical), mouse Dlg3 (99% identical), guinea pig DLG3 (99% identical), macaque DLG3 (99% identical), pig DLG3 (98% identical), rabbit DLG3 (98% identical), rat Dlg3 (98% identical), chimpanzee DLG3 (97% identical), zebrafish dlg3 (85% identical), tropical clawed frog dlg3 (79% identical). Paralogues in human: DLG2 (66% identical), DLG1 (65% identical), DLG4 (57% identical).
Diseases named in the same sentence as DLG3 in open-access papers:
DLG3 is named in the same sentence as 41 diseases in open-access papers, as found by Europe PMC text mining. Sharing a sentence is not in itself a finding about the gene and the disease. The quoted sentences say what the papers report.
Intellectual disability (9 papers, 2011 to 2025). "It is also noteworthy that EHMT targets include fly orthologs of NF1, FMR1, FMR2, CNTNAP2, GDI, DLG3, and of many more genes underlying syndromic and non-syndromic forms of intellectual disability." (PMID 21245904, 2011).
schizophrenia (8 papers, 2012 to 2023). A major psychotic disorder characterized by abnormalities in the perception or expression of reality. "Few studies had linked DLG4 variants to schizophrenia and NDDs such as ID and ASD; DLG2 variants to ASD, schizophrenia, and bipolar disorder; and truncating DLG3 variants to X-linked ID." (PMID 35457207, 2022).
breast carcinoma (7 papers, 2021 to 2025). "LncRNA MIAT bound to three DNMTs and increased DLG3 promoter methylation and suppressed DLG3 expression, which caused inactivation of the Hippo pathway and promotion of breast cancer progression." (PMID 35620052, 2022). "DLG3 was previously shown to have a role in oral squamous cell carcinoma, glioblastoma and breast cancer." (PMID 37948379, 2023). "Risk scores can effectively predict the prognosis and immunotherapy response of BC patients, in which DLG3 is a key gene that may be involved in shaping the immunosuppressive microenvironment of breast cancer, and down-regulation of DLG3 can inhibit M2 polarization of macrophages." (PMID 40881682, 2025). "According to previous studies, and the increase of Discs large homolog 3 (DLG3) gene can activate the Hippo signaling pathway and has the effect of suppressing further deterioration of GC, oral squamous cell carcinoma, breast cancer, colon cancer and lung cancer." (PMID 36712672, 2022). "Hypermethylation of the DLG3 promoter upregulates RAC1 and activates the PI3K/AKT signaling pathway, thereby promoting breast cancer progression." (PMID 40881682, 2025).
epilepsy (7 papers, 2013 to 2025). A brain disorder characterized by episodes of abnormally increased neuronal discharge resulting in transient episodes of sensory or motor neurological dysfunction, or psychic dysfunction. "Six novel DLG3 variants were identified in seven unrelated cases with heterogeneous epilepsies, including three with epilepsy and four with epilepsy and ID." (PMID 38249294, 2023). "In this study, we identified six novel DLG3 variants in seven unrelated patients with heterozygous epilepsies, including three with only epilepsy and four with epilepsy and NDD." (PMID 38249294, 2023). "These broad phenotypes of genes encoding proteins interacting with DLG3 protein provided possible clues for the association between DLG3 and epilepsy." (PMID 38249294, 2023). "We and others have reported SNV and InDel variants in DLG3 in cases characterized by mild to severe ID, mild dysmorphic features, language delay, and epilepsy in some patients." (PMID 33982443, 2021). "DLG3 variants were identified in seven unrelated cases with epilepsy." (PMID 38249294, 2023). "It is unknown whether DLG3 is associated with epilepsy and shares a broad phenotypic spectrum similar to NMDAR/NMDAR-associated genes." (PMID 38249294, 2023). "This hypothesis is supported by the fact that mutations in Dlg3, Psen1, Dnm1, and Ppp3ca have been found in epilepsy patients." (PMID 32033586, 2020). "Single nucleotide and InDel variants in DLG3 are known to cause a NDD with variable degrees of ID, dysmorphic features, language delay, and epilepsy in some cases." (PMID 33982443, 2021). "Increases in both PSD95 and DLG3 in cortex or post-synaptic fractions, respectively, have been described in brains of patients with focal cortical dysplasia and epilepsy." (PMID 23359859, 2013). "This study suggested that DLG3 variants were potentially associated with epilepsy with or without NDD." (PMID 38249294, 2023). "Protein-protein interaction network analysis revealed that DLG3 interacts with 52 genes with high confidence, in which the majority of disease-causing genes were associated with a wide spectrum of neurodevelopmental disorder (NDD) and epilepsy." (PMID 38249294, 2023). "We hypothesize that the upregulation of NMDAR interactors, such as Dlg3, Myh10, Ppp3a, Psen1, and Dnm1, may contribute to the anti-epilepsy phenotype by keeping the activity of NMDARs in control." (PMID 32033586, 2020). "Her younger son (IV-5) has epilepsy but is of normal intelligence and does not have the DLG3 mutation." (PMID 24721225, 2014). "This study suggested that DLG3 may be associated with epilepsy without neurodevelopmental disability." (PMID 38249294, 2023). "This study identified DLG3 variants in three patients with mild epilepsy without NDD, broadening the phenotypic spectrum of DLG3." (PMID 38249294, 2023).
X-linked intellectual disability (5 papers, 2018 to 2021). An X-linked intellectual deficiency in which not enough information is known, reported or published to indicate whether a gene causes non-syndromic or syndromic presentations. "Knockout mice have impaired synaptic plasticity and spatial learning, while human DLG3 mutations result in nonsyndromic X-linked intellectual disability." (PMID 32174962, 2020). "Dlg3 is implicated in X-linked intellectual disability, while Shank2 is a known risk gene for ASD; therefore, dysregulation of these genes may contribute to neurological and behavioral abnormalities." (PMID 34259631, 2021). "Dlg3 encodes synapse-associated protein 102 and is important for synapse formation in the brain, whereby knockout mice have synaptic plasticity impairments, including impaired spatial learning, and mutations in DLG3 cause non-syndromic X-linked intellectual disability." (PMID 32416732, 2020).
oral squamous cell carcinoma (4 papers, 2022 to 2024). "LINC01315 elevates the expression of discs large homolog 3 (DLG3) via sponging miR-211 and then delays oral squamous cell carcinoma (OSCC) progression." (PMID 35322763, 2022).
glioblastoma (3 papers, 2021 to 2025). The most malignant astrocytic tumor (WHO grade IV). "DLG3 is down-regulated in glioblastoma multiforme (GBM), and its overexpression induces mitotic cell cycle arrest and apoptosis, inhibiting proliferation and migration." (PMID 40881682, 2025).
neuroblastoma (3 papers, 2013 to 2017). Neuroblastoma (NB) is the most common solid, extracranial childhood tumor. "Together, these results indicate that miR-1246 play a potential role in the neurological process and cell death pathways by regulating DLG3 upon HEV71 infection in human neuroblastoma cells." (PMID 24739954, 2014). "In this study, we combined results from gene chips, mRNA assay, computational predictions, and dual luciferase assay to confirm miR-1246 directly targets DLG3 in HEV71-infected neuroblastoma cells." (PMID 24739954, 2014).
ovarian carcinoma (3 papers, 2012 to 2022). A malignant neoplasm originating from the surface ovarian epithelium. "DLG3 (discs large MAGUK scaffold protein 3) is upregulated in breast and ovarian carcinomas and downregulated in esophageal and papillary thyroid carcinoma." (PMID 35625354, 2022). "Previous studies have shown that DLG3 levels and its methylation showed an abnormal change in breast, renal, liver, lung, and ovarian cancers." (PMID 34765009, 2021). "The expression of COL3A1 in approximately 5 of the liver cancers, DLG3 in 5 of the liver, 7 lung and 5 ovarian cancers, and RN43 in 7 of the colon, 8 ovarian and 5 prostate cancers seemed to have higher expressions than the normal tissues." (PMID 23282184, 2012). "The average expression levels of DLG3 in breast, kidney, liver, lung, and ovarian cancers, and RNF43 in colon, liver, lung, ovarian, and prostate cancers were also found to be higher than their normal tissues." (PMID 23282184, 2012).
colon cancer (2 papers, 2020 to 2022). "Additionally, ADAD1 and DLG3, related to CD4+ T cells, were significantly associated with the prognosis of patients with colon cancer." (PMID 32571262, 2020).
prostate carcinoma (2 papers, 2012 to 2022). A carcinoma that arises from epithelial cells of the prostate gland. "There were no previous descriptions for the fusions NAIP:OCLN, PDE1C:DNAJC6, KANSL1:ARL17B, FOXP2:CREM, and AHSA1:DLG3 in the context of prostate cancer." (PMID 35625354, 2022).
Asperger syndrome (1 paper, 2014). "Of these, OPHN1, IGBP1, DLG3, NLGN3, and ZDHHC15 are associated with mental retardation or Asperger syndrome phenotypes." (PMID 24778889, 2014).
Dystonia (1 paper, 2025). An abnormally increased muscular tone that causes fixed abnormal postures. "DLG3 encodes the synapse-associated protein 102 (SAP102), a member of the membrane-associated guanylate kinase (MAGUK) protein family, and is implicated in dystonia-Parkinsonism syndromes." (PMID 40642607, 2025).
cancer (8 papers, 2012 to 2025). A tumor composed of atypical neoplastic, often pleomorphic cells that invade other tissues. "The results showed that DLG3 expression was negatively correlated with CD8T cell infiltration in a variety of cancers." (PMID 40881682, 2025). "GSEA demonstrated that many immune-related pathways, such as T-cell receptor signaling and Nod-like receptor signaling, were enriched in patients with high DLG3 expression in most cancer types." (PMID 40881682, 2025). "Mechanistically, upregulated DLG3 inhibits cancer progression by activating downstream Hippo signaling pathways." (PMID 37901333, 2023). "Upregulated MIAT exerts its carcinogenic effect by inhibiting downstream cancer suppressor DLG3, whereas silencing MIAT inhibits cell viability, migration and invasion, and EMT." (PMID 37901333, 2023). "Notably, homozygous variants private to the Min/J line were detected near candidate genes Myc and Dlg3 among other cancer related genes." (PMID 32600361, 2020). "To explore the inhibitory role of DLG3 in immunomodulation, we used different algorithms to assess DLG3 gene expression with CD8T cell infiltration in the Pan-cancer cohort." (PMID 40881682, 2025). "For example, male-amplified genes such as DLG3, PORCN, and PPFIA1 are involved in regulating postsynaptic membrane neurotransmitter receptor levels across multiple cancer types." (PMID 39716176, 2024). "The higher-than-normal tissue expression of COL3A1, DLG3, and RNF43 in some of the cancer tissues is in agreement with our in silico predictions." (PMID 23282184, 2012). "These genes have various implications for cancer therapy, and the detailed mechanism of action of DLG3, TGFB3, TGFBR1 and FZD6 genes in GC has not been studied, and needs further researches to explore." (PMID 36712672, 2022). "Interestingly, upon the real-time qPCR analysis of three cancer differentially expressed secreted protein gene candidates, COL3A1, DLG3, and RNF43 identified in this study, higher cancer expression levels of these genes in multiple cancer types were verified." (PMID 23282184, 2012). "First, correlation heatmaps showed that DLG3 expression was significantly negatively correlated with the vast majority of MHC molecules, cytokines and their receptors, and immunosuppressor/activator genes in BRCA, in addition to a similar trend in cancers such as BLCA, KIRC, etc.." (PMID 40881682, 2025).
neurodevelopmental disorder (7 papers, 2021 to 2025). A behavioral and cognitive disorder with onset during the developmental period that involves impaired or aberrant development of intellectual, motor, or social functions. "By interrogating all reported Xq13.1 duplications in individuals affected with a neurodevelopmental disorder, we provide evidence that this genomic region and particularly DLG3 might be sensitive to an increased dosage." (PMID 33982443, 2021).
neurological disorders (4 papers, 2016 to 2023). "Aside from the DLG3 gene mutations, abnormal expression of SAP102 in the hippocampus also contributes to the development of neurological diseases." (PMID 37928066, 2023). "It was also found that the expression of miR-1246, which was increased in EV71-infected cells (in agreement with our findings), could suppress the expression of the disc-large homolog 3 (DLG3), known to contribute to neurological disorders." (PMID 28531227, 2017).
tumor (2 papers, 2014 to 2025). "Firstly, we analyzed the differential expression of DLG3 in the tumor tissues and normal tissues, and the results showed that DLG3 mRNA expression in the TCGA cohort was significantly higher than that in normal tissues." (PMID 40881682, 2025). "Spatial transcriptome results of multiple BRCA samples all showed that DLG3 was mainly localized in tumor cells, while partially expressed in epithelial cells, macrophages, and fibroblasts." (PMID 40881682, 2025). "As Drosophila Dlg acts as a tumor suppressor regulating proliferation and asymmetric cell division, it is well possible that the Fltp–Dlg3 complex is involved in similar cellular processes in mammals." (PMID 25296022, 2014). "Finally, we analyzed the correlation of modeled genes with immune cells and showed that DLG3 was simultaneously significantly positively correlated with M2 macrophages and significantly negatively correlated with CD8T cells, suggesting its important role in the BC tumor microenvironment." (PMID 40881682, 2025).
infection (1 paper, 2014). The state of being infected such as from the introduction of a foreign agent such as serum, vaccine, antigenic substance or organism. "Finally, to clarify the relationship between miR-1246 and DLG3 regulation in response to HEV71 infection, varying doses of miR-1246 inhibitor were transfected to inhibit the induction of miR-1246." (PMID 24739954, 2014).
DLG3 also shares sentences with these, for which no sentence is quoted: bipolar disorder (3 papers); psychiatric disease (2); alcohol dependence (1); alcohol withdrawal syndrome (1); Allan-Herndon-Dudley syndrome (1); Alzheimer disease (1); autism (1); brain malformations (1); CHARGE syndrome (1); ciliopathies (1); Cognitive impairment (1); developmental delay (1); Focal cortical dysplasia (1); Huntington disease (1); invasive breast carcinoma (1); liver cancer (1); major depression (1); memory impairment (1); Nance-Horan syndrome (1); papillary thyroid carcinoma (1); type 2 diabetes mellitus (1); X-linked intellectual disability 90 (1); X-linked mental retardation syndrome (1).